CRYGC (crystallin gamma C)
Description:
Crystallins are the dominant structural components of the vertebrate eye lens.
Synonyms: CRYG3; CCL; CTRCT2
Tractability: No criterion of Open Targets' tractability assessment is met for any kind of drug.
Gene: Protein-coding gene on chromosome 2 (208,128,137 to 208,129,828, reverse strand). Ensembl gene ENSG00000163254.
Subcellular location (Human Protein Atlas): Cytosol; Vesicles
Gene Ontology:
Molecular function: protein binding; structural constituent of eye lens
Biological process: visual perception; lens development in camera-type eye
Cellular component: cytoplasm; nucleus
Genetic constraint (gnomAD): Loss-of-function variants: 14 observed, 23.26 expected, observed/expected ratio (o/e) 0.6, 90% interval 0.4 to 0.94. The upper end of that interval is the gene's LOEUF score, 0.94, which puts it in group 3 of 6, group 1 being the genes least tolerant of losing a copy. Missense variants: 235 observed, 245.4 expected, observed/expected ratio (o/e) 0.96, 90% interval 0.86 to 1.07. Synonymous variants: 96 observed, 95.48 expected, observed/expected ratio (o/e) 1.01, 90% interval 0.85 to 1.19.
Homologues: Orthologues: chimpanzee CRYGC (99% identical), macaque CRYGC (95% identical), pig CRYGC (88% identical), guinea pig CRYGC (87% identical), dog CRYGC (86% identical), mouse Crygc (85% identical), rat Crygc (85% identical). Paralogues in human: CRYGB (79% identical), CRYGA (75% identical), CRYGD (71% identical), CRYGS (53% identical), CRYBA4 (37% identical), CRYBB1 (36% identical), CRYBB3 (35% identical), CRYBA1 (34% identical), CRYBA2 (33% identical), CRYBG2 (33% identical), CRYBB2 (33% identical), CRYBG1 (31% identical), and 2 more.
Diseases named in the same sentence as CRYGC in open-access papers:
CRYGC is named in the same sentence as 17 diseases in open-access papers, as found by Europe PMC text mining. Sharing a sentence is not in itself a finding about the gene and the disease. The quoted sentences say what the papers report.
cataract (7 papers, 2009 to 2023). Partial or complete opacity of the crystalline lens of one or both eyes that decreases visual acuity and eventually results in blindness. "Among this set of candidate annotations, the gene WRN (“Werner syndrome, RecQ helicase-like”) was linked to the disease Werner syndrome and the gene CRYGC (“crystallin, gamma C”) was linked to cataracts." (PMID 23951102, 2013). "This study identified a disease-causing mutation c.471G>A in CRYGC in a Chinese family with cataracts, expanding the mutation spectrum of CRYGC causing congenital cataracts." (PMID 22876111, 2012). "Further biophysical studies of these mutant proteins will be required to provide insights regarding the molecular pathology of CRYGC-associated cataracts." (PMID 19204787, 2009). "The present study has identified a novel nonsense mutation in CRYGC associated with autosomal dominant cataracts and microcornea in a Chinese family." (PMID 19204787, 2009). "In summary, the present study has identified a novel nonsense W157X mutation in CRYGC associated with autosomal dominant cataracts and microcornea in a four-generation Chinese family." (PMID 19204787, 2009). "Our finding expands the spectrum of CRYGC mutations associated with congenital cataract and confirms the role of γ-crystallin in the pathogenesis of congenital nuclear cataracts." (PMID 19204787, 2009). "In this study, we investigated genetic variants in CRYAA, CRYAB, CRYGC, CRYGD, CRYBA1, GJA8, and GJA3 genes in 94 patients with congenital isolated cataracts from 45 unrelated families." (PMID 37367076, 2023).
nuclear cataract (6 papers, 2009 to 2020). A cataract (disease) that involves the lens nucleus. "At least four different mutations in CRYGC (T5P [Coppock-like cataract], GlyfsX62 [zonular pulverulent cataract], R168W [lamellar/nuclear cataract], and C109X [nuclear cataract]) have been reported to be associated with different phenotypes." (PMID 19262743, 2009). "Six novel CRYGC mutations (p.Asp65ThrfsX38, p.Arg142GlyfsX5, p.Arg142AlafsX22, p.Tyr144X, p.Arg169X, and p.Tyr46Asp) were identified in other six families with congenital nuclear cataracts, respectively." (PMID 28298635, 2017).
congenital cataracts (5 papers, 2012 to 2025). "Our findings expand the mutational spectrum of the CRYGC gene associated with congenital cataracts and provide enhanced insights into the molecular basis of this condition." (PMID 40776922, 2025). "The crystallin (CRYAA, CRYAB, CRYGC, CRYGD, and CRYBA1) and connexin (GJA8, GJA3) genes were analyzed in 45 unrelated families from the Volga–Ural Region (VUR) with hereditary congenital cataracts." (PMID 37367076, 2023).
Microcornea (5 papers, 2009 to 2021). A congenital abnormality of the cornea in which the cornea and the anterior segment of the eye are smaller than normal. "Mutations in CRYGC have previously been reported in patients with nuclear or lamellar cataract, microcornea and microphthalmia." (PMID 33923544, 2021). "Sequence variants in CRYGC have been associated with nuclear and lamellar cataract, along with additional eye anomalies such as glaucoma, microcornea, microphthalmia and optic disc coloboma." (PMID 33243271, 2020). "In conclusion, the present study has identified a nonsense mutation (c.471G>A, p.W157X) in CRYGC associated with autosomal dominant congenital nuclear cataracts and microcornea in a Chinese family." (PMID 22876111, 2012). "In this study, we report a nonsense mutation (c.471G>A) in exon 3 of CRYGC resulting in autosomal dominant congenital nuclear cataracts and microcornea in a four-generation Chinese family." (PMID 22876111, 2012). "Herein, we report the identification of a novel nonsense mutation (W157X) in processed CRYGC that cosegregated with autosomal dominant nuclear cataracts and microcornea in a four-generation Chinese family." (PMID 19204787, 2009).
autosomal dominant cataract (3 papers, 2009 to 2022). A syndromic cataract that has autosomal dominant inheritance. "Overall, we report four novel mutations in HSF4, CRYGA, CRYGC and PAX6, and one previously reported mutation in GJA3 that cause autosomal dominant congenital cataracts." (PMID 36670602, 2022). "Mutations in CRYGC and CRYGD have been identified to cause autosomal dominant congenital cataract as a result of altered stability, association and/or solubility of γ-crystallins." (PMID 22219628, 2011). "Mutations in the γ-crystallin gene (most commonly CRYGC and CRYGD) are responsible for multiple types of autosomal dominant cataracts, including pulverulent, aceuliform, cerulean, and lamellar cataracts." (PMID 22219628, 2011).
colon cancer (1 paper, 2020). "ESR2 and CHKA are also associated with colon and esophageal cancers, while CRYGC is only directly related to colon cancer according to the GeneCards database." (PMID 33273919, 2020).
lung carcinoma (1 paper, 2020). "No literature about the expression status of CRYGC in lung cancer was found." (PMID 33273919, 2020).
CRYGC also shares sentences with these, for which no sentence is quoted: microphthalmia (2 papers); cancer (1); Coppock-like cataracts (1); coralliform cataract (1); esophageal cancer (1); glaucoma (1); lamellar cataracts (1); optic disc coloboma (1); tumor (1); Werner syndrome (1).